MGMT (O-6-methylguanine-DNA methyltransferase)
Diseases named in the same sentence as MGMT in open-access papers (continued):
Sharing a sentence is not in itself a finding about the gene and the disease.
tumor (continued). "There are indications that patients with epigenetic silencing of the DNA-repair protein MGMT in the tumor tissue benefit the most from TMZ, however, pediatric GBMs seldom display methylated MGMT promoters." (PMID 39949745, 2025). "Analysis of this patient’s tumor from initial diagnosis was consistent with an IDH wildtype, MGMT promoter methylated HGG, and TMB of 18 mt/Mb." (PMID 40134851, 2025). "Within this context, MGMT promoter methylation emerges as a focal epigenetic event, where CIMP silences the DNA repair gene MGMT, thereby enhancing tumor sensitivity to alkylating agents like temozolomide." (PMID 40426960, 2025). "Consistent with this high efficacy, expression of the MGMT (O6-methylguanine–DNA methyltransferase) DNA-repair protein, a major contributor to TMZ resistance was undetectable in the patient tumor." (PMID 39416100, 2025). "O6-methylguanine-DNA methyltransferase (MGMT) is a DNA repair enzyme, and its promoter methylation status is closely related to the sensitivity of tumor cells to alkylating agent chemotherapy drugs." (PMID 41394878, 2025). "LPHNs-cRGD suppressed MGMT expression, enhanced GBM cell vulnerability to TMZ, and extended the survival of tumor-bearing mice." (PMID 40771723, 2025). "Boxplots depict the protein expression levels (Z-values) of ATRX, OLIG2, MGMT, and IDH2 in normal tissue samples (n = 10, blue) and primary tumor samples (n = 99, red)." (PMID 40282990, 2025). "In contrast, significant differences were observed in the distribution of age, tumor grade, IDH-status, chr-1q-19-codeletion, and MGMT-promoter-status between the two groups (P < 0.001)." (PMID 40554484, 2025). "This is in agreement with our prior finding that maximum TMZ-induced tumor cell death occurs at CT4, which corresponds to the time in the data presented here when daily MGMT protein levels are near their peak." (PMID 41123669, 2025). "We also examined changes in serum tumor markers and inflammatory factors in Th-NET patients, presenting the expression status of SSTR2 and MGMT in pathological evaluations, thereby filling a significant data void in Th-NET research." (PMID 39061142, 2024). "This has been largely attributed to the gain of resistance by tumor cells that survived TMZ, through the increased expression of DNA O-6-methylguanine methyltransferase (MGMT): a mechanism called chemoresistance." (PMID 39194524, 2024). "This synergy is further highlighted by the significant reduction in MGMT expression and mitochondrial respiration in GBM cells, showcasing a potent approach to inhibit tumor survival mechanisms." (PMID 39103871, 2024). "Those patients with available tumor genotyping data were relatively split between IDH mutant and wild type (N = 91 missing) as well as MGMT methylated and unmethylated (N = 450 missing)." (PMID 38601343, 2024). "This process involves testing key genes such as isocitrate dehydrogenase (IDH) and O6-methylguanine-DNA methyltransferase (MGMT) promoter methylation, which determine tumor classification and treatment resistance." (PMID 39123366, 2024). "On the other hand, relevance because the accumulation of oncometabolites in tumor cells renders them sensitive to DSBs and also to alkylation DNA damage through the inhibition of HRR, AlkB and MGMT repair systems, respectively." (PMID 39201738, 2024).
tumor (continued). "Using luciferase as a readout for tumor cells in the LEGO model, we found that PTCC LEGO is more sensitive than the other two to TMZ, in line with a higher MGMT promoter methylation status." (PMID 38273014, 2024). "By applying TMZ to a MGMT-methylated GBM PDOX model, we identified both tumor cell and TME remodeling." (PMID 38566128, 2024). "The prognostic value is especially valuable in elderly and/or frail patients, in whom the MGMT promoter methylation status should always be assessed before deciding on therapy, as patients without methylated tumors may benefit to a much smaller extent from tumor-specific treatment and chemotherapy." (PMID 38571509, 2024). "This comprehensive analysis highlights the intricate role of H3K9ac, SP1, and MGMT in GBM subtypes, particularly in the context of tumor recurrence and TMZ resistance." (PMID 38448295, 2024). "Interference with β‐Catenin re‐sensitizes tumor cells to TMZ and significantly reduces the cytotoxic effects of high‐dose TMZ treatment, and MGMT overexpression counteracts the effects of β‐Catenin deficiency." (PMID 39041891, 2024). "We then examined the impact of tumour mRNA levels of CABLES1, FAM35A, MGMT and PPP2R5C on PFS in the AGO-OVAR 11 study, and in the publicly available TCGA datasets." (PMID 38443389, 2024). "When the promoter region of MGMT is hypermethylated, however, the cellular level of MGMT protein is decreased, leaving the effects of TMZ unchallenged, leading to tumor cell death via intact mismatch repair (MMR) mechanisms." (PMID 39012509, 2024). "Prognostic factors like MGMT (O6-methylguanine-DNA methyltransferase) promoter methylation status, extent of resection (EOR), residual tumor volume, functional level, and age, are well established." (PMID 39531176, 2024). "TMZ’s efficacy depends on the methylation status of the O6-methylguanine-DNA methyltransferase (MGMT) promoter, which can increase tumor cell sensitivity to its DNA-damaging effects." (PMID 39063215, 2024). "More noteworthy, high expression of MGMT in immunohistochemistry and GBM were correlation to tumor progression." (PMID 39118481, 2024). "O-6-methylguanine-DNA methyltransferase (MGMT), a DNA repair enzyme, removes alkylated lesions from tumor DNA, thereby promoting chemoresistance." (PMID 38224404, 2024). "For instance, in GBM stem‐like cells (GSCs) with methylated O6‐methylguanine‐DNA methyltransferase promoter (MGMT‐m), CHI3L1 functioned as a tumour suppressor gene, sensitizing GSCs' response to temozolomide (TMZ) by activating DNA damage responses (DDRs)." (PMID 37902124, 2023). "In recent years, beyond the molecular factors (i.e., MGMT and IDH1/2), circulating markers of inflammation and immune components within the tumor tissue have been the focus of attention in oncology as potential prognostic factors." (PMID 37584750, 2023). "Tumor biopsies displayed an enhanced EZH2 and Myc expression in both MGMT promoter methylated and unmethylated tissues, particularly in MGMT promoter unmethylated ones." (PMID 37147437, 2023). "In consistent with these observations, measuring O6-mG levels by binding intensity of MGMT C145S mutant with O6-mG revealed that 6-MP and TMZ combination greatly increased O6-mG levels in tumor tissues when comparing with TMZ treatment alone." (PMID 37737247, 2023). "On 43 GBM, they observed a low number of CD3+in larger tumor size, a low CD4+ in methylated MGMT and a low CD8+ related to methylation." (PMID 37584750, 2023).
tumor (continued). "miR-370-3p suppresses MGMT expression in GBM cells and sensitive glioma cells to TMZ, inducing apoptosis of tumor cells." (PMID 37371047, 2023). "We further analysed the impact of a range of factors, not previously well studied in this cohort of patients, such as the size of the tumour, location along the carpus callosum and the molecular signatures (IDH and MGMT methylation status)." (PMID 37665387, 2023). "Both in the training and validation cohorts, the GA-MSCRGPI revealed satisfactory prognostic efficiency, such as age, tumor grade, IDH status, 1p19q codel status and MGMT promoter unmethylated status." (PMID 37005685, 2023). "To further assess the relationship between tumor cellularity, driver VAF, and MGMT assay outcomes, we performed additional analyses on 5 IDHwt GBM samples." (PMID 37919784, 2023). "Pretreatment tumor biopsies were collected for whole-exome sequencing (WES), and multiplex quantitative immunofluorescence (QIF) of MGMT protein expression and immune markers." (PMID 37387791, 2023). "Cell line and original tumor share the majority of CNV alterations, including losses in Chr 9/10 that included PTEN and MGMT and gains in Chr 20, which included amplification of PDGFRA, CDK4, and MDM2." (PMID 37958846, 2023). "For histopathology confirmation and diagnosis, MGMT gene methylation, and IDH-1/-2 status, the tumor biopsies were sent to the sites’ hospital pathology laboratory." (PMID 37137304, 2023). "As an MGMT transcription factor, the activation and nucleation of Tyr705 in STAT3 are critical for DNA damage repair in tumor cells." (PMID 38071213, 2023). "The training cohort used to build the model contains comprehensive clinical information (such as tumor location, resection range, ATRX expression, and MGMT promoter methylation), which helped to create a robust model." (PMID 37340065, 2023). "While intracranial CW implantation appeared to control local tumor recurrence, TMZ administration was used to synergistically resensitize mTOR suppression in order to modulate MGMT protein expression." (PMID 35646111, 2022). "The MGMT promoter methylation, migration, proliferation, and TMZ-response of the tumor cells were examined at different time points." (PMID 35563629, 2022). "The data indicate that DNA methylation (MGMT) and malfunction of GPI anchoring (PGAP3) are distinct mechanisms that are relevant for tumor progression and relapse." (PMID 34529172, 2022). "In SCC, genes that are commonly hypermethylated to repress their expression and tumor-suppressive activities include CDKN2A and RASSF1 (growth arrest), MGMT (DNA repair), and DAPK (apoptosis)." (PMID 35912167, 2022). "In case of surgically removed NETs, the primary tumor was tested for ALK and MGMT promoter methylation." (PMID 35677534, 2022). "MGMT transfers the methyl group from guanine, thereby repairing damaged DNA and counteracting the cytotoxic effects of TMZ on tumor cells." (PMID 35806212, 2022). "While most of them eventually develop tumor progression and acquired resistance to TMZ, the available evidence indicates that both MGMT promoter methylation status and MGMT protein remain relatively stable during GBM progress and TMZ treatment." (PMID 36316307, 2022). "Therefore, silencing the MGMT gene could enhance the sensitivity of tumor cells to TMZ." (PMID 35207516, 2022). "A total of 59 patients were excluded due to missing either MGMT methylation, epidermal growth factor receptor amplification, WHO performance status, or planned tumor volume (PTV)." (PMID 35371528, 2022). "Histopathological and molecular characterization of tumors was achieved considering tumor grade according to 2016 WHO and several biomarkers (i.e., IDH-1, TERT, MGMT, DEL1p/19q, Ki-67)." (PMID 35720068, 2022). "In one case of a 59 year old patient with an IDH mutant and MGMT methylated GBM, tumor biopsy was performed 2 months prior to [68Ga]Ga-PSMA PET/MRI." (PMID 36119502, 2022).
tumor (continued). "This was in keeping with observations for the MGMT- and HGA cell lines, thus suggesting a TMZ-based selection of tumor cells with a higher proliferation rate." (PMID 35563629, 2022). "It was found that GSC tumor showed strong expression of Ki-67, moderate expression of EGFR and VEGF, and weak expression of MGMT and HIF-1α." (PMID 36591483, 2022). "The current Cyto-C study was designed to prospectively evaluate and validate the prognostic value of tumor CcO activity in patients with newly diagnosed primary GBM, and compared to the known prognostic value of MGMT promoter methylation status." (PMID 35088051, 2022). "Our present study mainly discovered the downregulation of XIST and MGMT as well as the upregulation of miR-221-3p in HCC cells and tumor specimens." (PMID 35723009, 2022). "We next analyzed associations between VMP1 expression and clinical pathological parameters, including the tumor grade, isocitrate dehydrogenase (IDH) status, 1p/19q codeletion, TERT status, and O6-methylguanine DNA methyltransferase (MGMT) promoter status." (PMID 34311746, 2021). "In this study, we found a significantly higher percentage of cells showing positive staining with the antibody to MGMT in PT tissue than in GBM, independently from the presence of tumor cells in the former area." (PMID 33562724, 2021). "For better exploring the MGMT effect on the PP-induced enhanced anti-tumor effect of TMZ chemotherapy, the scrambled control or MGMT cDNA plasmid was transfected into LN18 and T98G cells." (PMID 34642308, 2021). "O6-methylguanine DNA methyltransferase (MGMT) is a DNA-repair enzyme that repairs DNA adducts at the O6 position of guanine, which prevents the death of tumor cells via alkylation." (PMID 33810154, 2021). "Alterations in DNA repair mechanisms, especially in the O-6-methylguanine-DNA methyltransferase (MGMT) enzyme, are thought to contribute to initial TMZ resistance and tumor relapse." (PMID 33807183, 2021). "Another study added perfusion MRI to the multimodal MRI and demonstrated important features for identifying MGMT as increased relative CBV in T1C and a higher ratio of contrast-enhancing tumor to complete tumor volume." (PMID 34676470, 2021). "Tumor induction of nuclear biomarkers of DNA damage response (DDR) γH2AX, pNBs1, and Rad51 was assessed in the context of MGMT and MMR protein expression for expansion cohort patients." (PMID 33216844, 2020). "We investigated all patients for fusions with FGFR, neurotrophin tyrosine receptor kinase (NTRK), and MET and identified NTRK2 in one patient with a MGMT‐methylated tumor and FGFR3‐TACC3 in 3 patients (2.8%) all of which were in MGMT‐unmethylated tumors." (PMID 32885540, 2020). "The promoter region of some tumor-suppressor genes, including CDH1 and MGMT, has been shown to become hyper-methylated during EBV-induced primary B-cell transformation." (PMID 32483241, 2020). "GBM response to TMZ is modulated by O-6-methylguanine-DNA methyltransferase (MGMT), which drives TMZ resistance when overexpressed by tumours." (PMID 32366909, 2020). "The highest classification accuracy included age, preoperative tumor volume computed on T2-wheighted MRI, preoperative ΔT1/T2 MRI Index, EOR, and MGMT methylation status." (PMID 32046132, 2020). "Methylation of the MGMT promoter in GBM effectively silences this DNA repair gene, making tumor cells unable to repair the cytotoxic O6-methylguanine lesions induced by TMZ and some other alkylating agents." (PMID 32218600, 2020). "It is very unusual for patients diagnosed with unmethylated MGMT tumors to respond to any therapy given to them, which implies that anti-CMV therapy likely affects their tumor cells." (PMID 32987955, 2020).
tumor (continued). "The initial molecular phenotype of this tumor was IDH-wildtype, MGMT promoter unmethylated status, and 1p intact/19q intact." (PMID 33317554, 2020). "Subgroup analysis revealed that the low tumor purity has dismal prognosis in the female, G-GIMP subtype, proneural subtype, and MGMT promoter methylated patients." (PMID 32021566, 2020). "It is of interest to note that patients with dual MGMT inactivation received a higher number of adjuvant TMZ cycles (P < .001) during therapeutic management at diagnosis and during revision surgery at tumor progression (P = .04)." (PMID 32666673, 2020). "In this study, the methylation status of five selected gene promoters (CDKN2A, hMLH1, MGMT, CSF2, and DIS3L2) confirmed the presence of DNA methylation in tumor tissues and matched normal tissues." (PMID 31924802, 2020). "Several studies in animal models have suggested that the therapy of MGMT gene silence was able to overcome TMZ resistance and increase tumor cell death." (PMID 33628188, 2020). "The following variables were involved; age ≥ 65 years, MGMT methylation status, FLAIR-T2 abnormality ≥ 60 cm3 or ≥ 2,000 mm3 and FLAIR-T2/tumor ratio ≥ 5 for all methods." (PMID 32984040, 2020). "In contrast, the common IDH1 (R132H) mutation is known to induce a hypermethylation phenotype in gliomas by silencing MGMT (and other mismatch repair [MMR] genes) thus sensitizing the tumor to TMZ-induced mutagenesis." (PMID 31376079, 2020). "To further investigate the relationship between MGMT promoter methylation status and the expression of Tim-3 in GBM, we retrieved 84 specimens from a tumor tissue bank." (PMID 33041828, 2020). "In looking at variables with significant relation to survival in our results, CPH model documented that age, MGMT promoter, surgical completeness, IDH gene and KPS had a significant or trend toward relation with tumor progression." (PMID 33194609, 2020). "Their study found that greater EOR of enhancing tumor tissues can significantly prolong PFS and OS in MGMT promoter methylated GBMs but can only prolong OS in MGMT promoter unmethylated GBMs." (PMID 32922947, 2020). "In total, 10 features, including age, sex, symptom duration, tumor location, WHO grade, surgical intervention, IDH status, MGMT promoter status, CTVhr volume, and CTVlr volume, were collected from each patient." (PMID 33194609, 2020). "Extensively studied prognostic factors of survival include age, Karnofsky Performance Score (KPS), extent of tumor resection (EOR), residual tumor volume (RTV), O-6-Methylguanine Methyltransferase (MGMT) promoter methylation status, and Ki-67 expression." (PMID 31036031, 2019). "In another man in his 50’s with right temporal GBM with an unmethylated MGMT promotor, an MRI scan after 12 cycles of adjuvant TMZ treatment showed complete remission of the tumor (left), and Met-PET demonstrated low uptake (Tmax/Nave, 1.52) (middle)." (PMID 31780768, 2019). "The direct repair protein methylguanine DNA methyltransferase (MGMT) removes the cytotoxic O6-methylguanine (O6-MeG) lesion delivered by TMZ and so its expression by tumours confers TMZ-resistance." (PMID 35582280, 2019). "At univariate analysis ECOG-PS, Sex (female), extensive tumor resection was shown to be related to a longer PFS, while MGMT expression (cut-off 70%) to a shorter PFS." (PMID 30678211, 2019). "O6 methylguanine-DNA methyltransferase (MGMT) is an enzyme that is able to transfer the methyl-adduct from O6 guanine to cysteine residue, which effectively repair the DNA alteration in tumor cells prior to replication." (PMID 31814867, 2019). "Promoter regions of tumor suppressor genes hMLH1, MGMT, APC, and CDH1 were found to be hypermethylated in early stages of tumor formation in colon adenocarcinomas." (PMID 31244652, 2019). "Tumor suppressor gene MGMT, along with RASSF1A and FHIT gene promoter hypermethylation, is correlated with tumor stage and metastasis." (PMID 31244652, 2019).